IFNG (interferon gamma)
Diseases named in the same sentence as IFNG in open-access papers (continued):
Sharing a sentence is not in itself a finding about the gene and the disease.
tumor (continued). "This was accompanied by the induction of a transcriptional profile in dendritic cells that suggested enhanced antigen cross‐presentation, as well as IFNγ‐mediated upregulation of genes associated with antigen processing and presentation in tumour cells." (PMID 38711203, 2024). "Together, this suggests an induction of IFNγ signalling in the tumour epithelium of Dock2 deficient mice." (PMID 39242821, 2024). "Interferon- γ encoded by the IFNG is a cytokine that can enhance the activity of macrophages and T lymphocytes, and kill tumor cells through the body’s immune mechanisms." (PMID 39314848, 2024). "Here, we showed that IFITM3-deficient Tregs blunted tumor growth by strengthening the tumor-killing response and displayed the Th1-like Treg phenotype with higher secretion of IFNγ." (PMID 38167862, 2024). "Consistent with this notion, cisplatin-induced GSDME-dependent pyroptosis increased the levels of TILs and cytokines associated with T cell activation (TNFα and IFNγ) in the tumor tissue." (PMID 38391959, 2024). "Promising predictive molecular biomarkers for neoadjuvant immunotherapy are tumor mutational burden and the interferon-gamma pathway expression signature." (PMID 38540282, 2024). "Low in vitro inducibility of MHC-I and PD-L1 by IFNγ was associated with increased tumor outgrowth of MOC1 clones in vivo." (PMID 39009951, 2024). "Gene aberrations in APM, including loss of 20S proteasome subunits and tumor-intrinsic loss of MHC-I, as well as mutations in IFNγ response pathway genes have been reported as hallmarks of PD-1 or PD-L1 ICB resistance due to loss of tumor immune recognition." (PMID 38427670, 2024). "PreI was calculated as the percentages of CD3+IFNγ+ cells after in vitro co-cultures of PBMCs with peptides against four different Tumor-Associated Antigens (TAA)." (PMID 39001455, 2024). "Their presence translates into suppressed tumor growth, linked with an upregulation of IFNγ and IL-12 secretion and inhibition of angiogenesis." (PMID 38338661, 2024). "We compared the effect of PTPN2/N1 inhibition to genetic deletion and found that AC484 dose-dependently enhanced IFNγ-driven growth arrest in vitro, comparable to Ptpn2/n1-deficient B16 tumour cells." (PMID 37794185, 2023). "Immune cells from peripheral blood, spleen, and ascites from these mice displayed heightened activation and interferon-gamma production when exposed to autologous tumor-associated antigens." (PMID 38235131, 2023). "Our work provides insight into stem-like T cell regulation at the tumor site by providing a mechanism whereby IFNγ sensing induces the loss of stem-like T cells." (PMID 36658158, 2023). "In summary, the deletion of the EBD of IFNγ leads to fatal immunopathology caused by local expression in the tumor tissue." (PMID 36732425, 2023). "Both IFNγ and TNFα promote M1 macrophage polarisation, and induction of M1 macrophages is associated with reduced tumour burden in mouse CRC." (PMID 37455828, 2023). "A single dose caused a marked reduction in tumor growth that was concomitant with increased IFNγ levels; increased Th1, CTL, and activated NK cells; a shift in macrophages from the M2 to M1 phenotype; and a reduction in Treg cells." (PMID 38250068, 2023). "Type II IFNs, such as IFNγ, are hallmark cytokines produced by tumor-infiltrating lymphocytes (TILs), such as NK and T cells, and their activation leads to tumor clearance through multiple mechanisms." (PMID 36900204, 2023). "Low-CAFRS tumors were closely associated with tumor immunity, including adaptive immune responses, T-cell activation, interferon-gamma responses, cytokine–receptor interaction and lymphocyte-mediated immunity." (PMID 38235137, 2023). "Tumor cells harboring such mutations exhibit decreased tumor immunogenicity and/or IFNγ insensitivity, leading to evasion of T‐cell‐mediated anti‐tumor immunity and resistance to immunotherapy." (PMID 37452654, 2023).
tumor (continued). "Our previous work identified that IFNγ upregulates NAMPT in tumor-associated macrophages and is important for their anti-tumorigenic function." (PMID 36900204, 2023). "IFNγ has a dual role in cancer immunity (reviewed in 33) and is implicated in tumor immune surveillance through the induction of tumor cell cycle arrest, senescence, and death." (PMID 37638024, 2023). "Transcriptomic profiling revealed that AC484-treated and Ptpn2/n1-deficient tumour cells had highly similar global transcriptional responses to IFNγ treatment." (PMID 37794185, 2023). "Adding a neutralizing IFNγ antibody to anti-PD-L1/TGFβ treatment completely inhibited the anti-tumor response caused by the combination, demonstrating the IFNγ dependency of the dual blockade." (PMID 37543621, 2023). "An antibody-cytokine fusion protein consisting of the L19 antibody (specific to the alternatively spliced extra domain B of Fibronectin “EDB”) in scFv format fused to a murine IFNγ variant has previously been studied in tumor-bearing mice." (PMID 36839699, 2023). "Third, the method captures tumor-immune interactions in the context of diverse immune-associated phenotypes such as immune infiltration, immune cell types, IFNγ expression, or inflammation signatures." (PMID 37106127, 2023). "High tumor miR-181a levels were also associated with decreased STING expression which correlated with a consistent decrease in interferon gamma (IFNG) response and lymphocyte infiltration in patients with HGSOC." (PMID 37932806, 2023). "This excessive IFNγ increases the “fragility” of Treg cells, causing autoimmunity and, conversely, enhancing anti-tumor immunity." (PMID 38201290, 2023). "CD39+ expression has been correlated with tumor-specific recognition and is associated with reduced IFNγ and IL2 expression." (PMID 36689623, 2023). "Hot tumors, also known as immune inflammatory tumors, are characterized by high levels of T cell infiltration, elevated interferon-gamma signaling pathways, increased PD-L1 expression, and a high tumor mutation burden." (PMID 37547717, 2023). "T cell function was assessed by unstimulated HLA-DR expression or interferon gamma (IFN-γ) production with Enzyme-linked ImmunoSpot assays following stimulation with virus or tumour-associated antigens." (PMID 37252426, 2023). "Loss of the PBAF components increase tumor cell sensitivity to IFNγ stimulation, enhance its chemokine secretion, and subsequent recruitment of effector T cells." (PMID 37427373, 2023). "Our observations showed that CD70 and CD274 are co-associated with IFNγ expression and are predominantly expressed in different immune cell types within the tumor microenvironment." (PMID 37106127, 2023). "Patients with a higher interferon gamma response to one tumour-associated antigen at baseline were more likely to have an excellent response to nivolumab therapy (described as a >90% metabolic tumour volume reduction)." (PMID 37958391, 2023). "Classically activated (M1) macrophages exhibit tumor-killing activity after exposure to interferon γ (IFNγ) and cause tissue destructive reactions." (PMID 37039038, 2023). "The infiltration of CD8+ T cells and CD4+ Th1 cells at the tumor site is a hallmark of a favorable tumor prognosis, due to their production of the cytokines IFNγ and TNFα, which can effectively induce the cell cycle of tumor cells to arrest in the G1/G0 phase." (PMID 37545500, 2023). "IFNγ’s effect on reprogramming has been studied in tumor-associated macrophages, whereby IFNγ affects many important metabolic regulators to alter metabolism." (PMID 36900204, 2023). "Because IFNγ is inherently linked to the efficacy of tumor immunity, it is critical to fully understand how it can also simultaneously impede tumor immunity." (PMID 36658158, 2023).
tumor (continued). "In Pant-treated mice, tumor-associated myeloid and lymphoid cells displayed signatures of IFNγ-driven activation." (PMID 37833072, 2023). "The downregulation of the IL6 and IL12B cytokines and the IFNG responses in TNBC tumor samples were associated with significantly poor responses to neoadjuvant therapies that included olaparib." (PMID 37932806, 2023). "Remotely, the indole‐producing bacteria in the gut microbiome‐derived indole compounds activated the AhR receptor in tumor‐associated macrophages to suppress tumor growth and intra‐tumoral infiltration of IFNγ+CD8+ T cells in pancreatic cancer." (PMID 37771912, 2023). "T cells from tumor-bearing Stat1-deficient mice display attenuated IFNγ production and upregulation of immunosuppressive cytokines." (PMID 37444444, 2023). "Genetic deficiencies in the IFNγ pathway in the tumor cells hinders activation of the regulatory factor IRF1 and subsequent transcription of the PD-L1 gene." (PMID 37620318, 2023). "Specifically, a subset of tumor-associated macrophages can secrete Type I interferons such as IFNγ, IFNβ, and IFNα within the local tumor environment." (PMID 36911698, 2023). "After afami-cel, fold increases in serum IFNγ levels relative to baseline were associated with anti-tumor response; this was more evident in SS than other tumors." (PMID 36624315, 2023). "In this work, we investigate IFNγ-driven reprogramming of gene expression in tumour cells associated with acquired resistance to ICBT, therein demonstrating a role for the IFNγ target gene product poly-ADP ribosyl polymerase 14 (PARP14)." (PMID 37752135, 2023). "Correspondingly, the delay in tumor outgrowth associated with IDO1 loss was likewise overcome by the concomitant loss of IFNγ." (PMID 37182174, 2023). "Gene set enrichment analysis (GSEA) showed that upregulation of various inflammatory and interferon gamma-related signatures was strongly linked with tumor shrinkage." (PMID 37433281, 2023). "Our data demonstrate that as a result of IFNγ-R1 stabilization, STUB1 loss leads to enhanced IFNγ response as well as to strong sensitization to cytotoxic T cell-mediated tumor cell killing in vitro." (PMID 35395848, 2022). "On the contrary, IFNγ-secreting γδ T cells were associated with tumor regression and thrived in a glucose-rich environment." (PMID 36140808, 2022). "Tumor associated macrophages (TAMs) are polarized to an anti-tumor M1 phenotype in response to pro-inflammatory factors such as IFNγ, GM-CSF and lipopolysaccharide." (PMID 35273619, 2022). "In a randomized clinical trial with inoperable metastatic CRC patients, low-dose CY treatment resulted in delayed tumor progression associated with an increase in IFNγ+ anti-tumor T-cell responses, and reduction of Treg cells, B cells, and NK cells." (PMID 35874729, 2022). "have highlighted the role of intracellular NAMPT (iNAMPT) in mediating the effects of IFNγ in tumor-associated macrophages." (PMID 35402885, 2022). "Molecularly, our data suggest that cognate interaction with IFNγ-producing CD4 T cells can disengage the TAMs from their tumor-associated genetic programs and divert them instead to a tumor-rejecting program." (PMID 35903540, 2022). "Th1 cytokines, such as IL‐1β, IL‐2, IL‐12, IL‐18, TNFα, and IFNγ, are associated with proinflammation, while Th2 cytokines, such as IL‐4, IL‐5, and TGFβ, play a suppressive role in the tumour immune microenvironment." (PMID 35430766, 2022). "And the pathway enrichment was also conducted based on the 50 classical HALLMARK tumor pathways, we observed the activation of interferon gamma response, allograft rejection, complement and epithelial mesenchymal transition." (PMID 36468024, 2022). "Antibody-mediated neutralization of IFNγ in ILC2-deficient Apc1322T/+ mice resulted in an increase in the number and size of tumors, revealing that increased IFNγ production contributed to the decreased tumor burden observed in ILC2-deficient mice." (PMID 35658010, 2022).
tumor (continued). "T cells exhaustion, defined by the progressive loss of effector function after persistent infection or tumor antigens, lose the ability to produce cytokines, such as IFNγ, TNFα, and IL-2." (PMID 36050760, 2022). "Firstly, the induced expression mediated by adaptive immunity and attributed to IFNγ signaling between TCs and ICs; PD-L1 expression is induced and dependent on the immunogenicity, the tumor mutational burden, and/or local TIL density within the tumor." (PMID 35626035, 2022). "After two days of co-culture with EGFR CAR T cells, resistant clones of tumor cells were enriched for loss of genes involved in IFNγ-mediated signaling, such as IFNGR1 and JAK1." (PMID 36189315, 2022). "Th1 cytokines such as interferon γ (IFNγ), TNFα, or granulocyte/monocyte-colony-stimulating factor (GM-CSF) are implicated in tumor immunosurveillance and regulate cytotoxic activity." (PMID 36614001, 2022). "As the predominant suppressor cells of the immune system, Tregs promote the M2-like tumor-associated macrophages accumulation in the TME by inhibiting IFNγ from CD8+ T cells, which enhances their metabolic fitness and pro-tumor gene expression." (PMID 36582227, 2022). "Loss of STUB1 sensitized tumour cells to IFNγ exposure and led to statistically significant enrichment of the protein targets of ISGs, including those required for antigen presentation such as H2-K1, B2M, PSME1, PSME2 and ERAP1." (PMID 35982220, 2022). "This was supported by a second experiment whereby administration of UCART123 cells in mice harboring the same PDX at a lower tumor burden, was associated with drastically lower IFNγ levels and translated into long-term survival of UCART123-treated animals." (PMID 35484100, 2022). "This T cell enrichment in tumor cell regions was associated with a marked increase in ICAM-1 expression on tumor cells and was inhibited by a blocking monoclonal IFNγ antibody." (PMID 36189315, 2022). "An important role of CD8+ T cells is associated both with the secretion of effector cytokines (IFNγ, TNFα), which are involved in the priming and differentiation of cytotoxic cells, and in the direct destruction of infected and tumor cells." (PMID 36560509, 2022). "Within the TME, these actions by IFNγ promote the conversion of M2-like TAMs into M1 phenotypes, causing them to incite anti-tumor activity." (PMID 36031601, 2022). "EBV infection causes expression of viral proteins in tumor cells such as latent membrane protein 1 (LMP1) in addition to the activation of interferon-gamma (IFN-γ)." (PMID 36233023, 2022). "CD8+ cytotoxic T cells perform an instrumental function in anti-tumour immunity by killing tumour cells, and can also inhibit angiogenesis by secreting interferon-gamma (IFN-γ), which is widely believed to be linked to improved prognosis of tumour patients." (PMID 36743929, 2022). "GSEA showed that the interferon alpha response and the interferon gamma response (two tumor hallmarks) were enriched in the high-risk subgroup." (PMID 35444701, 2022). "IFNγ signaling has been associated with anti-tumor cytotoxicity in neutrophils, as well as maturation of monocytes and DCs, which can lead to the activation of tumoricidal NK and T-cells." (PMID 36479083, 2022). "In vivo, PDCD4-deficient effector CD8 T cells also exhibited increased IFNγ production in tumor models, resulting in delayed tumor growth." (PMID 34983947, 2022). "Whereas wildtype tumor cells moderately upregulated IFNγ-R1 expression upon treatment with increasing amounts of IFNγ, STUB1-deficient cells further elevated IFNγ-R1 protein levels, particularly the heavier, cell-surface isoforms." (PMID 35395848, 2022).
tumor (continued). "Nevertheless, tumor cells can lose responsiveness to IFNγ by loss of IFNGR and mutations in the IFNγ signaling pathway, which participates in tumor immune evasion." (PMID 35269922, 2022). "Widespread APOBEC damage leads to tumour suppressor loss and creates neoantigens, which were significantly more abundant in IFNγ-signaturehigh basal/squamous tumours." (PMID 36358715, 2022). "As a result of this stimulation, antigen-specific CD4 T cells produce IFNγ causing a phenotypical and functional switch in the TAMs, from tumor nurturing to an inflammatory M1-like phenotype." (PMID 35903540, 2022). "Exhausted/dysfunctional CD8+ T cells, anti-inflammatory/M2-like tumor-associated macrophages (TAMs), defects in IFNγ signaling or antigen processing and presentation all contribute to resistance." (PMID 36091022, 2022). "Momentum for STING agonists grew after preclinical studies involving STING-deficient tumor-bearing mice were demonstrated as having fewer IFNγ-producing CD8+ T cells with increased Tregs and MDSCs." (PMID 36031601, 2022). "The secretion of IFNγ is often associated with host defense towards foreign pathogens and is known to aid in tumor surveillance and the anti-tumor response." (PMID 36110853, 2022). "IL-25 promotes tumorigenesis through activating ILC2s which sustain tumour M-MDSCs to suppress T cell and IFNγ-mediated anti-tumour immunity.IL-33 deficiency is associated with a reduction in tumour Tregs and mast cells." (PMID 36263033, 2022). "Low levels of IFNγ in the TME increase the risk of tumor metastasis during immunotherapy, indicating that IFNγ induces cancer progression." (PMID 35281822, 2022). "Fucoidan from Undariapinnatifida (Phaeophyceae) sporophyll increased survival in P-388 tumor-bearing mice, which was linked to the enhancement of natural killer (NK) lymphocyte activity and increased interferon-gamma production by T cells." (PMID 35999584, 2022). "Blockage of IL-4 on murine mregDC1 have shown to restore IFNγ-mediated IL-12 production and cause reduction in tumor growth." (PMID 36230990, 2022). "This notion was further backed by the continuously increased expressions of IL2, TNFα/β and IFNγ in tumor-associated CD8+ T cell in BAY-I and BAY-I withdrawal groups." (PMID 35013322, 2022). "CXCR5+CD8 T cells from human peripheral blood mononuclear cells, tumor tissues and tumor associated lymph nodes upregulate effector molecules such as IFNγ, TNFα, granzyme B, and perforin compared to CXCR5−CD8 T cells." (PMID 36314014, 2022). "Recent interest has focused on blocking immune inhibitory pathways, with IFNγ again implicated in tumour growth inhibition following immune checkpoint blockade." (PMID 36358715, 2022). "In both models, the beneficial effect of blocking type I IFN after administration was negated by blocking type II IFN simultaneously, which is in line with reports in patients with tumour defects in IFNγ signalling associated with acquired resistance to ICB31." (PMID 35986006, 2022). "Positive associations were significant between interferon-gamma response and ssGSEA scores of the tumor intermediate state and the CD8+ T exhausted state in the TCGA-SKCM cohort (intermediate: R = 0.46, p < 2.2e-16; exhausted: R = 0.62, p < 2.2e-16)." (PMID 35903095, 2022). "IFNG is important for anti-tumor immune activity; research has shown that the tumor genetic mutations that disrupt the IFNG pathway signaling facilitate resistance to ICIs." (PMID 35493449, 2022). "S11C), suggesting that there are additional IFNγ-producing immune cell populations such as Th1 and γδ T cells that contribute to the reduced tumor burden observed in ILC2-deficient mice." (PMID 35658010, 2022). "The development of tumors is promoted by cytokines G-CSF, IFNγ, TNFα, IL-10, and IL-12p70 released by neoplastic cells and tumor-associated macrophages (TAM)." (PMID 35463072, 2022).